SMARCC1 (SWI/SNF related BAF chromatin remodeling complex subunit C1)
Description:
Involved in transcriptional activation and repression of select genes by chromatin remodeling (alteration of DNA-nucleosome topology). Component of SWI/SNF chromatin remodeling complexes that carry out key enzymatic activities, changing chromatin structure by altering DNA-histone contacts within a nucleosome in an ATP-dependent manner. May stimulate the ATPase activity of the catalytic subunit of the complex. Belongs to the neural progenitors-specific chromatin remodeling complex (npBAF complex) and the neuron-specific chromatin remodeling complex (nBAF complex). During neural development a switch from a stem/progenitor to a postmitotic chromatin remodeling mechanism occurs as neurons exit the cell cycle and become committed to their adult state. The transition from proliferating neural stem/progenitor cells to postmitotic neurons requires a switch in subunit composition of the npBAF and nBAF complexes. As neural progenitors exit mitosis and differentiate into neurons, npBAF complexes which contain ACTL6A/BAF53A and PHF10/BAF45A, are exchanged for homologous alternative ACTL6B/BAF53B and DPF1/BAF45B or DPF3/BAF45C subunits in neuron-specific complexes (nBAF). The npBAF complex is essential for the self-renewal/proliferative capacity of the multipotent neural stem cells. The nBAF complex along with CREST plays a role regulating the activity of genes essential for dendrite growth (By similarity).
Synonyms: BAF155; SRG3; Rsc8; CRACC1; HYC5; SWI3
Tractability: PROTAC: UniProt records ubiquitination sites on it; ubiquitination databases record sites on it; its protein half-life has been measured.
Gene: Protein-coding gene on chromosome 3 (47,585,269 to 47,782,106, reverse strand). Ensembl gene ENSG00000173473.
Subcellular location: Nucleus; Cytoplasm
Subcellular location (Human Protein Atlas): Nucleoplasm
Pathways (Reactome):
Chromatin organization: Formation of neuronal progenitor and neuronal BAF (npBAF and nBAF); Formation of the canonical BAF (cBAF) complex; Formation of the embryonic stem cell BAF (esBAF) complex; Formation of the non-canonical BAF (ncBAF) complex; Formation of the polybromo-BAF (pBAF) complex; RMTs methylate histone arginines
Gene expression (Transcription): RUNX1 interacts with co-factors whose precise effect on RUNX1 targets is not known; Regulation of endogenous retroelements by Piwi-interacting RNAs (piRNAs)
Developmental Biology: Regulation of MITF-M-dependent genes involved in pigmentation
Gene Ontology:
Molecular function: ATP-dependent chromatin remodeler activity; nucleosomal DNA binding; protein binding; histone binding; transcription coactivator activity; chromatin binding
Biological process: chromatin remodeling; positive regulation of DNA-templated transcription; negative regulation of cell differentiation; positive regulation of cell differentiation; positive regulation of cell population proliferation; positive regulation of double-strand break repair; positive regulation of myoblast differentiation; positive regulation of stem cell population maintenance; positive regulation of T cell differentiation; regulation of G0 to G1 transition; regulation of G1/S transition of mitotic cell cycle; regulation of mitotic metaphase/anaphase transition; regulation of nucleotide-excision repair; regulation of transcription by RNA polymerase II; nucleosome disassembly; prostate gland development; regulation of DNA-templated transcription
Cellular component: chromatin; cytoplasm; nucleoplasm; nucleus; protein-containing complex; SWI/SNF complex; brahma complex; GBAF complex; kinetochore; nBAF complex; npBAF complex; nuclear matrix; RSC-type complex; XY body
Genetic constraint (gnomAD): Loss-of-function variants: 17 observed, 69.09 expected, observed/expected ratio (o/e) 0.25, 90% interval 0.17 to 0.37. The upper end of that interval is the gene's LOEUF score, 0.37, which puts it in group 1 of 6, group 1 being the genes least tolerant of losing a copy. Missense variants: 650 observed, 805.75 expected, observed/expected ratio (o/e) 0.81, 90% interval 0.76 to 0.86. Synonymous variants: 331 observed, 301.41 expected, observed/expected ratio (o/e) 1.1, 90% interval 1 to 1.2.
Gene-disease validity (ClinGen):
ClinGen rates the evidence that SMARCC1 causes each of these diseases.
SMARCC1-associated developmental dysgenesis syndrome (autosomal dominant): Definitive. Variants in SMARCC1 cause a novel human syndrome characterized by developmental delay, cerebral ventriculomegaly and aqueductal stenosis, and other associated structural brain and cardiac defects.
Homologues: Orthologues: chimpanzee SMARCC1 (99% identical), dog SMARCC1 (97% identical), pig SMARCC1 (96% identical), mouse Smarcc1 (96% identical), guinea pig SMARCC1 (96% identical), macaque SMARCC1 (95% identical), rat Smarcc1 (95% identical), rabbit SMARCC1 (88% identical), tropical clawed frog smarcc1 (78% identical), zebrafish smarcc1a (70% identical), zebrafish smarcc1b (56% identical). Paralogues in human: SMARCC2 (64% identical), MYSM1 (12% identical), MPND (7% identical).
Diseases named in the same sentence as SMARCC1 in open-access papers:
SMARCC1 is named in the same sentence as 84 diseases in open-access papers, as found by Europe PMC text mining. Sharing a sentence is not in itself a finding about the gene and the disease. The quoted sentences say what the papers report.
breast cancer (24 papers, 2014 to 2026). A primary or metastatic malignant neoplasm involving the breast. "Stratification analyses by breast cancer subtypes identified three proteins, SMARCC1, LSP1, and NCKAP1L, associated with luminal A, luminal B, and ER-positive breast cancer." (PMID 39468330, 2024). "Analyses stratified by breast cancer subtypes found that SMARCC1, LSP1, and NCKAP1L are associated with luminal A and LSP1 with luminal B and ER-positive subtype." (PMID 39468330, 2024). "CARM1-mediated SMARCC1 methylation is an independent prognostic biomarker for the recurrence and metastasis of breast cancer." (PMID 35669562, 2022). "The specificity of used antibody against BAF155 and BRM was validated on breast cancer cell line with amiRNA targeting SMARCC1 or SMARCA2." (PMID 32073734, 2020). "Western blotting of PARP1 co-immunoprecipitated proteins confirmed the direct interaction of PARP1 with ARID1A and BRG1, but also with other subunits of SWI/SNF, such as SMARCC1 and SMARCC2, in the studied breast cancer cell lines." (PMID 31614656, 2019). "SMARCC1 was not reported in previous TWAS or PWAS studies for breast cancer." (PMID 39468330, 2024).
colorectal cancer (6 papers, 2009 to 2021). A primary or metastatic malignant neoplasm that affects the colon or rectum. "Based on the Oncomine database, we screened the mRNA expression profiles of SMARCC1 across a number of studies for different types of tumors (normal vs. cancer), including colorectal cancer, leukemia and sarcoma." (PMID 34937564, 2021). "In prostate cancer and colorectal carcinoma, SMARCC1 was suggested to contribute, at least partially, to tumorigenesis." (PMID 34937564, 2021). "Human BAF170 (SMARCC2) and BAF155 (SMARCC1), the homologs of Swi3p, are involved in cancers since BAF170 and BAF155 mutations were found in gastric and colorectal cancers and small cell lung cancers, respectively." (PMID 31623074, 2019). "SMARCC1 protein upregulation has been reported in prostate cancer, colorectal cancer and cervical intraepithelial neoplasia." (PMID 23874428, 2013). "SMARCC1 is altered in prostate and colorectal cancer and SMARCA5 is known to be dysregulated in leukemia and up-regulated in human breast tumors." (PMID 21811619, 2011). "Notably, some studies demonstrated that SMARCC1 was correlated with proliferation and metastasis in prostate cancer and colorectal carcinoma." (PMID 34937564, 2021).
prostate carcinoma (6 papers, 2009 to 2025). A carcinoma that arises from epithelial cells of the prostate gland. "In agreement with this, and with a previous report on the subcellular location of SMARCC1 in prostate cancer, we found SMARCC1 to be located in the nucleus." (PMID 19156145, 2009).
bladder cancer (5 papers, 2021 to 2025). "We found that both the mRNA and protein expression levels of SMARCC1 were increased in bladder cancer, and increased SMARCC1 expression was significantly associated with a higher T stage and poorer prognosis in bladder cancer patients." (PMID 35669562, 2022). "The levels of SMARCC1 (encoding BAF155 protein) mRNA and protein expression are increased in bladder cancer, and this heightened expression is strongly linked to advanced T stage and unfavourable prognosis in patients with bladder cancer." (PMID 39779467, 2025). "And CCK-8, transwell assay, cell apoptosis assay, cell cycle analysis and subcutaneous tumor model were conducted to explore the role of SMARCC1 in carcinogenesis of bladder cancer." (PMID 35669562, 2022). "SMARCC1 (encoding BAF155 protein) translocates into the nucleus via KPNA2 and functions as an oncogenic gene, downregulation of SMARCC1 (Encoding BAF155 protein) expression results in G1/S phase arrest and an increase in apoptotic cells in bladder cancer." (PMID 39779467, 2025). "And KPNA2 was co-expressed with SMARCC1 in cell nucleus of bladder cancer." (PMID 35669562, 2022). "In addition, immunofluorescence staining results showed that most of the endogenous SMARCC1 protein was located in the nucleus and only a little of SMARCC1 protein was expressed in the cytoplasm of bladder cancer cells." (PMID 35669562, 2022). "Compared to patients with negative expression of SMARCC1, patients with high expression of SMARCC1 in bladder cancer have a lower survival rate." (PMID 39779467, 2025).
ovarian carcinoma (5 papers, 2021 to 2024). A malignant neoplasm originating from the surface ovarian epithelium. "Other amplified oncogenes frequently found in epithelial ovarian cancer were ERBB2, STAT3, PIK3C2B, CDK2, and CDK4, as well as SWI/SNF chromatin modification complex genes, including ARID1A and SMARCC1." (PMID 36430324, 2022).
pancreatic cancer (5 papers, 2013 to 2022). "IHC analysis demonstrated homogeneous nuclear staining of SMARCC1 in normal pancreatic ductal cells, whereas variable expression was observed in the pancreatic cancer lesions." (PMID 31769422, 2019). "Of note, the possible contribution of lowered expression of several of these genes in human tumors is already proven, like PAFAH1B1 in non-small cell lung cancer, SMARCC1 in pancreatic cancer and NKN2 in myeloproliferative neoplasm (MPN) precursors." (PMID 26113842, 2015). "Further studies in gemcitabine resistant clones of pancreatic cancer cell lines MIA PaCa-2 and PSN1 showed decreased expression of SMARCC1." (PMID 31769422, 2019).
congenital hydrocephalus (4 papers, 2022 to 2026). Hydrocephalus that is present at birth. "Of note, variants in the SMARCC1 gene are reportedly associated with the RTT-like phenotype, as well as congenital hydrocephalus." (PMID 37761403, 2023). "Molecular studies on congenital hydrocephalus show that, exome sequencing of 125 CH trios and 52 additional probands identified 3 genes with significant burden of rare damaging de novo or transmitted mutations, in addition to TRIM71, there are SMARCC1 and PTCH1." (PMID 35356930, 2022).
breast tumors (3 papers, 2011 to 2021). "Analyses of human breast tumors indicate that SOX4 mRNA is uniformly overexpressed in basal-like tumors relative to adjacent normal tissue along with the SWI/SNF catalytic subunit SMARCA4 and SMARCB1 SMARCC1, SMARCD2, and ACTL6A, which encode for the essential subunits of this complex." (PMID 33837205, 2021).
Hydrocephalus (3 papers, 2019 to 2025). Hydrocephalus is an active distension of the ventricular system of the brain resulting from inadequate passage of CSF from its point of production within the cerebral ventricles to its point of absorption into the systemic circulation. "Five genes (TRIM71, SMARCC1, PTEN, PIK3C, MTOR) were found to be involved in syndromic forms of hydrocephalus, and three other genes (FMN2, FOXJ1 and PTCH1) to be responsible for severe hydrocephalus with AS stenosis." (PMID 34092257, 2021).
lung adenocarcinoma (3 papers, 2013 to 2021). A carcinoma that arises from the lung and is characterized by the presence of malignant glandular epithelial cells. "Taken together, further research is required on SMARCC1, SMARCC2, and SMARCA5, together with TOP1, as predictive biomarkers of resistance to geldanamycin derivatives as HSP90 inhibitors in lung adenocarcinoma." (PMID 33802597, 2021). "These genes include SMARCC1, TRA2B, CBX3 and PRPF6 that show the same upregulation pattern as EGFR in lung adenocarcinoma and we have reported all the mentioned genes for the first time in lung adenocarcinoma." (PMID 23874428, 2013).
lung carcinoma (3 papers, 2020 to 2025). "The effects of LSD1 silencing are unique for mESCs and F9 cells, as silencing of LSD1 in human embryonic kidney carcinoma 293 T and lung carcinoma H1299 cells that express both SMARCC1 and SMARCC2 did not exhibit any proliferation defects." (PMID 36335117, 2022).
neuroblastoma (3 papers, 2022 to 2025). Neuroblastoma (NB) is the most common solid, extracranial childhood tumor. "A proteomic analysis reveals SMARCC1, ARID1A and ARID1B are mainly related to chromatin remodeling in neuroblastoma." (PMID 41142119, 2025).
sarcoma (3 papers, 2021 to 2023). A usually aggressive malignant neoplasm of the soft tissue or bone. "Among the seven survival-associated mRNAs, the high expression levels of SMARCC1, SRSF10, PRPF38A, JARID2 and GNAI3 were significantly associated with shorter overall survival in sarcomas (P = 0.0018, P = 0.037, P = 0.0058, P = 0.0093, and P = 0.0234, respectively)." (PMID 33653335, 2021). "Among them, high expression levels of SMARCC1, SRSF10, PRPF38A, JARID2, GNAI3, miR-301a-3p, miR-106b-5p, miRNA-130b-3p, miR-423-3p and LINC01296 and low expression levels of ARF3 and PRKCB were associated with shorter overall survival in sarcomas." (PMID 33653335, 2021).
colon cancer (2 papers, 2019 to 2024). "To investigate whether ASS1 is required to succinate SMARCC1, we first measured SMARCC1 levels in the chromatin-bound fraction following DNA damage in colon cancer cells without ASS1." (PMID 38858597, 2024).
embryonic carcinoma (2 papers, 2022 to 2024). "Mouse embryonic stem cells (mESCs) and mouse F9 embryonic carcinoma cells uniquely express a specific mSWI/SNF complex, the esBAF complex, that only contains SMARCC1 but not SMARCC24–7." (PMID 36335117, 2022).
glioma (2 papers, 2022 to 2023). A benign or malignant brain and spinal cord tumor that arises from glial cells (astrocytes, oligodendrocytes, ependymal cells). "The peroxisome hallmark geneset notably includes IDH1 and 2, SMARCC1 (also part of Myc targets v1), transcription factors part of PD1 target associated with survival and immune signaling in glioma." (PMID 37637066, 2023).
viral infection (2 papers, 2024 to 2025). "PBRM1 is a chromatin modulator of the SWI/SNF chromatin remodeling complex, which includes SMARCA4, SMARCB1, SMARCC1, ARID1A, DPF2, and SMARCE1, also implicated in ACE2 expression regulation and, thus, in host cell susceptibility to viral infection." (PMID 40378209, 2025).
adenoma (1 paper, 2009). A neoplasm arising from the epithelium. "The frequency and intensity of SMARCC1 staining increased borderline significantly (P=0.078, Fisher's exact test) from adenoma to adenocarcinoma, but not from adenocarcinoma to liver metastases." (PMID 19156145, 2009).
asthma (1 paper, 2023). "These four genes, SMARCC1, SETD2, KMT2B, and CHD8, were used to construct a nomogram model for predicting the prognosis of patients with severe asthma." (PMID 37245015, 2023). "The nomogram constructed using the four CRs, SMARCC1, SETD2, KMT2B, and CHD8, may be a useful tool for predicting the prognosis of patients with severe asthma." (PMID 37245015, 2023).
astrocytoma (1 paper, 2021). "It has been reported that IFNγ treatment can modulate the expression of BAF155/SMARCC1 in human astrocytoma cell lines." (PMID 33809795, 2021).
cervical carcinoma (1 paper, 2022). A carcinoma arising from either the exocervical squamous epithelium or the endocervical glandular epithelium. "To test whether SMARCC1 or SMARCC2 is regulated by SET7, we used siRNA-mediated silencing of SET7 with two representative siRNAs41 and found that loss of SET7 indeed increased the levels of both SMARCC1 and SMARCC2 proteins in human cervical carcinoma HeLa cells." (PMID 36335117, 2022).
Coffin-Siris syndrome (1 paper, 2019). Coffin-Siris syndrome (CSS) is a rare congenital multi-systemic genetic disorder characterized by aplasia or hypoplasia of the distal phalanx or nail of the fifth digit, developmental delay, intellectual disability, coarse facial features, and other variable clinical manifestations. "Sequence variants in other BAF complex genes are associated with other neurodevelopmental disorders including SMARCC1/2, PBRM1, ARID1A/B and SMARCA4 in ASD, PBRM1 and ARID1B in schizophrenia, SMARCB1 in Kleefstra syndrome, and ARID1A/B, SMARCA4, SMARCB1, and SMARCE1 Coffin-Siris syndrome (CSS)." (PMID 31288860, 2019).
congenital heart disease (1 paper, 2017). A heart disease that is present at birth. "In fact, a recent whole exome sequencing study identified a de-novo SMARCC1 missense mutation in a patient with congenital heart disease, supporting the sensitivity of the heart to perturbations of the SMARCC1." (PMID 28753627, 2017).
endometriosis (1 paper, 2023). The growth of functional endometrial tissue in anatomic sites outside the uterine body. "Seven genes, namely, APPL1, CSNK2A1, ERG, KDM4A, SMARCC1, SUZ12 and TRIM25, were selected to establish the diagnostic model for endometriosis, and a nomogram was constructed based on them." (PMID 36860677, 2023).
epilepsy (1 paper, 2023). A brain disorder characterized by episodes of abnormally increased neuronal discharge resulting in transient episodes of sensory or motor neurological dysfunction, or psychic dysfunction. "Interestingly, among multiple CRF genes, only SMARCA2, SMARCB1, ACTL6B and KDM5C have been previously associated with epilepsy, and some other members of this cluster (e.g., SMARCC1, SMARCC2, SMARCA4 and WRD5) are only cursorily mentioned among epilepsy candidate genes." (PMID 36982355, 2023).
malignant mesothelioma (1 paper, 2020). A malignant neoplasm of the pleura or peritoneum, arising from mesothelial cells. "Indeed, our most important finding is the lack of alterations involving BAP1, SETD2, NF2, CDKN2A, PBRM1, and SMARCC1 genes consistently mutated or deleted in malignant mesotheliomas." (PMID 32545767, 2020). "The WDPMs lacked the alterations involving BAP1, SETD2, NF2, CDKN2A/B, LASTS1/2, PBRM1, and SMARCC1 that are frequently found in malignant mesotheliomas." (PMID 32545767, 2020).
prostate adenocarcinoma (1 paper, 2021). "Our finding showed that SMARCC1 was significantly downregulated in prostate adenocarcinoma, with a higher Gleason score (GS) than that in low GS." (PMID 34249931, 2021).
pulmonary stenosis (1 paper, 2020). "We also report novel plausible gene–disease associations for tetralogy of Fallot/pulmonary stenosis (CDC42BPA, FGD5), hypoplastic left or right heart (SMARCC1, TLN2, TRPM4, VASP), congenitally corrected transposition of the great arteries (UBXN10), and early-onset cardiomyopathy (TPCN1)." (PMID 32037394, 2020).